LGALS1 (galectin 1)
Diseases named in the same sentence as LGALS1 in open-access papers (continued):
Sharing a sentence is not in itself a finding about the gene and the disease.
chronic kidney disease (5 papers, 2020 to 2022). Impairment of the renal function secondary to chronic kidney damage persisting for three or more months. "Galectin-1 (Gal-1), a member of the β-galactoside binding protein family, is associated with inflammation and chronic kidney disease." (PMID 34559847, 2021). "Galectin-1 modulates acute and chronic inflammation, and is associated with glucose homeostasis and chronic renal disease." (PMID 31996694, 2020). "In a proteomics study, galectin-1 was also higher in the kidneys of mice with surgically induced chronic kidney disease, and a study on kidney fibrosis in mice reports that galectin-1 levels are significantly higher in the kidneys of animals with both type 1 and T2D." (PMID 36295832, 2022). "We examined whether circulating galectin-1 can predict incidence of chronic kidney disease (CKD) and type 2 diabetes in a middle-aged population, and if Mendelian randomisation (MR) can provide evidence for causal direction of effects." (PMID 34743218, 2022).
chronic pancreatitis (5 papers, 2014 to 2023). A chronic inflammatory process causing damage and fibrosis of the pancreatic parenchyma. "In chronic pancreatitis group, the Galectin-1 staining intensity in stromal cells was only significantly associated with alcohol-drinking (p = 0.04)." (PMID 24595374, 2014). "Our immunohistochemical results indicated that increased Galectin-1 staining in chronic pancreatitis was found significant correlation with alcohol drinking, which have been proved to able to activate the PSCs and result in Galectin-1 expression." (PMID 24595374, 2014). "Galectin-1 was revealed with low abundance in the normal pancreas, moderately to intensely expressed in fibroblasts of chronic pancreatitis samples, and strongly expressed in the stroma surrounding the cancer mass but negative in cancer cells." (PMID 24595374, 2014). "The results implied that in chronic pancreatitis the Galectin-1 expression was associated with the alcohol-drinking, but in PDAC Galectin-1 expression was obviously related with tumor biological characteristics." (PMID 24595374, 2014). "The results indicated that the expression of Galectin-1 increased gradually from normal pancreas, chronic pancreatitis to PDAC." (PMID 24595374, 2014). "The sensitivity and specificity of galectin-1 serum levels were similar to that of CA19-9 in PDAC, but serum levels were also increased in patients with chronic pancreatitis." (PMID 32055023, 2020). "The relationship between immunohistochemistry staining intensity of Galectin-1 and clinicopathologic variables were assessed in 66 PDAC tissues, 18 chronic pancreatitis tissues and 10 normal controls." (PMID 24595374, 2014). "We showed that Galectin-1 protein was gradually increased from normal pancreas, chronic pancreatitis to PDAC, and in PDAC Galectin-1 protein expression was also increased from well, moderately to poorly differentiated PDAC." (PMID 24595374, 2014). "Galectin-1 was negative in normal pancreas, whereas weak or moderate staining was mainly observed in the mesenchymal of chronic pancreatitis tissues." (PMID 24595374, 2014). "Galectin-1 expression was gradually increased from normal pancreas (negative), chronic pancreatitis (weak) to PDAC (strong), in which Galectin-1 expression was also increased from well, moderately to poorly differentiated PDAC." (PMID 24595374, 2014).
diabetic nephropathy (5 papers, 2011 to 2024). "Galectin-1 is implicated in the pro-fibrotic processes observed in diabetic nephropathy and CKD through the PI3K/Akt signaling pathway." (PMID 39769262, 2024). "While we have already discussed the potential influence of galectin-1 in diabetic kidney disease and retinopathy, galectin-1 has also been linked to lymphatic remodelling, although not in the context of T2D." (PMID 36295832, 2022). "Galectin 1 is involved in vascular smooth muscle cell proliferation and Galectin 3 has been associated with diabetic nephropathy and atherogenesis." (PMID 21600003, 2011). "Galectin-1 is strongly associated with lower kidney function in cross-sectional analyses, and two-sample MR analyses suggest a causal protective effect on kidney function among individuals with type 2 diabetes at high risk of diabetic nephropathy." (PMID 34743218, 2022). "In conclusion, galectin-1 shows a strong cross-sectional association with decreased kidney function, but two-sample MR analyses suggest a causal protective effect of galectin-1 on kidney function among participants with type 2 diabetes at high risk of diabetic nephropathy." (PMID 34743218, 2022). "The authors conclude that galectin-1 is linked to lower kidney function in cross-sectional analyses but that MR analyses suggest a protective effect on kidney function in subjects at high risk of diabetic nephropathy." (PMID 36295832, 2022). "However, in individuals with type 2 diabetes from ANDIS who belonged to the severe insulin-resistant diabetes subgroup and were at high risk of diabetic nephropathy, genetically elevated galectin-1 was significantly associated with higher eGFR (p = 5.7 × 10−3)." (PMID 34743218, 2022). "Our MR analysis indicates a potential renal protective effect of galectin-1 based on our observation that genetically elevated levels of galectin-1 are associated with higher eGFR in an independent study population of individuals with type 2 diabetes at high risk of diabetic nephropathy." (PMID 34743218, 2022). "In human studies, increased galectin-1 expression was reported in renal biopsy samples from individuals with diabetic kidney disease, and silencing of galectin-1 in podocytes preserved the phenotype during high-glucose stress." (PMID 34743218, 2022). "A smaller study including eight individuals with diabetic nephropathy and three healthy controls suggested increased levels of galectin-1 in the renal tissue of individuals with diabetic nephropathy." (PMID 36295832, 2022).
endometriosis (5 papers, 2014 to 2025). The growth of functional endometrial tissue in anatomic sites outside the uterine body. "LGALS1 is a widely expressed lectin in a family of proteins implicated in inflammation, endometriosis, and cancer." (PMID 30154697, 2018). "The molecule responsible for modulating p38 MAPK and PKA/SERCA2 signalling was galectin-1, as demonstrated using a mouse model of endometriosis." (PMID 41226294, 2025). "Analogically to galectin-1, galectin-3 expression was enhanced in endometriosis and eutopic endometrium of endometriosis patients." (PMID 36612107, 2022). "Among several known galectins, there are galectin-1, -3 and -9 which are engaged in both progression of endometriosis and OCs." (PMID 36612107, 2022). "Galectin-1 was shown to be over-expressed both in the endometriotic lesions and in eutopic endometrium of patients with endometriosis." (PMID 36612107, 2022). "Galectin-1 affects cell motility, signal transduction, and vascularisation and is overexpressed in both the ectopic and eutopic endometrium of women diagnosed with endometriosis." (PMID 41226294, 2025). "We then examined how CRH and UCN regulate galectin-1 expression in an endometrial adenocarcinoma cell line, used as a eutopic epithelial endometrium model, aiming to further elucidate the role of these molecules in eutopic endometrium and infertility problems of women with endometriosis." (PMID 25473847, 2014). "Immunohistochemistry and western blot analysis were performed in order to identify galectin-1 expression in ectopic and eutopic endometrium of women with and without endometriosis and the regulatory effect of CRH and UCN on galectin-1 expression." (PMID 25473847, 2014). "Finally, based on these results, showing that the CRH upregulative effect on galectin-1 is mediated by CRHR1, the potential use of Antalarmin could be reinforced in accessing the immune disequilibrium noticed in eutopic and ectopic endometrium of women with endometriosis." (PMID 25473847, 2014).
heart failure (5 papers, 2020 to 2025). Inability of the heart to pump blood at an adequate rate to meet tissue metabolic requirements. "Individuals with higher galectin-1 levels also had greater prevalence of heart failure, peripheral artery disease, and prior history of stroke." (PMID 33244142, 2020).
Hypertension (5 papers, 2017 to 2025). The presence of chronic increased pressure in the systemic arterial system. "There were several genes affected by high-intensity interval training during HFD hypertension, which were Trim39, Nr4a1, Plekhf1, Tgm2, Lgals1, Egr1, and Atf3." (PMID 41516177, 2025). "More importantly, the negative regulation on CaV1.2 channels function by Galectin-1 was found to effectively and stably control hypertension in spontaneously hypertensive rats when Galectin-1 was overexpressed in smooth muscles using adeno-associated virus as a vector." (PMID 36818347, 2023). "Lgals1 expression was downregulated by high-intensity interval training, which might have the potential to reduce the apoptosis rate during HFD hypertension in the cortex." (PMID 41516177, 2025).
lung adenocarcinoma (5 papers, 2011 to 2022). A carcinoma that arises from the lung and is characterized by the presence of malignant glandular epithelial cells. "It has been showed in experimental study, that increased galectin-1 expression was associated with high levels of invasion in lung adenocarcinoma and oral squamous cell carcinoma lines." (PMID 22024187, 2011). "Several investigations had explored the possible mechanism of galectin-1 promoting tumor progression and chemoresistance in lung adenocarcinoma." (PMID 35280768, 2022). "Galectin-1 expression was found to be up-regulated in cisplatin-resistant human lung adenocarcinoma A549/DDP cells compared with their parental cells." (PMID 28842515, 2017). "Expression of Galectin-1 in lung adenocarcinoma cells (CL1-0 and A549) promoted EMT, migration, and invasion; knockdown of Galectin-1 in these cells reversed EMT and inhibited migration and invasion." (PMID 26491213, 2015). "By using tumor cells derived from patients with lung adenocarcinoma, we found that galectin-1 is highly overexpressed in the CD133+ cancer cells as compared to the normal cancer cells (CD133−) from the same patients." (PMID 25605013, 2015). "Future research on the mechanism of galectin-1 affecting radiation response in lung adenocarcinoma may be worth exploring." (PMID 35280768, 2022). "Since radiation therapy was the main locoregional therapy modality in this population, the result implied that tumor galectin-1 might be a biomarker to predict radiation response in the patients with lung adenocarcinoma." (PMID 35280768, 2022). "Consequently, in this study, we investigated the prognostic impact of galectin-1 overexpression as well as galectin-3 overexpression on the patients with lung adenocarcinoma after definitive radiation therapy." (PMID 35280768, 2022). "In our study, we also found that overexpression of tumor galectin-1 had the trend of worse OS, and significantly worse LRPFS and DMFS in a cohort of 41 lung adenocarcinoma patients after radiation therapy." (PMID 35280768, 2022). "The overexpression of tumor galectin-1, but not galectin-3, is associated with poor LRPFS of patients with lung adenocarcinoma after thoracic radiation therapy." (PMID 35280768, 2022). "In this study, we found that overexpression of tumor galectin-1 was the most significant prognosticator to predict worse LRPFS in patients with lung adenocarcinoma after thoracic radiation therapy without concurrent chemotherapy." (PMID 35280768, 2022). "Taken together, these findings suggested that galectin-1 plays a major role on the tumorigenesis and invasiveness of CD133+ cancer cells and might serve as a potential therapeutic target for treatment of human patients with lung adenocarcinoma." (PMID 25605013, 2015).
metastatic disease (5 papers, 2015 to 2025). "Serum galectin-1 levels were significantly higher in patients with metastatic disease compared with patients with localized tumors." (PMID 26589590, 2015). "Finally, lower galectin-1 levels correlated with previous metastatic disease, and abnormal galectin-1 levels correlated with decreased overall survival in NSCLC." (PMID 38539500, 2024). "Although the patients that had lower galectin-1 levels were more likely to have previous metastatic disease, serum galectin-1, -3, and -9 levels did not predict future metastasis." (PMID 38539500, 2024). "Furthermore, we found PSC-derived Galectin-1 significantly promoted invasion and metastasis (by inducing EMT) of both orthotopic and metastatic tumors in vivo." (PMID 29156810, 2017). "A significant difference was detected in serum galectin-1 between EOC patients with non-metastatic and those with metastatic disease, but not between EOC patients and healthy volunteers." (PMID 26589590, 2015). "However, a significant difference in serum galectin-1 was seen between EOC patients with non-metastatic and those with metastatic disease (P = 0.034)." (PMID 26589590, 2015).
oral squamous cell carcinoma (5 papers, 2011 to 2026). "Galectin-1 and galectin-3 are intriguing markers for oral squamous cell carcinoma for the screening of higher risk populations." (PMID 31832021, 2019).
periodontitis (5 papers, 2021 to 2026). An acute or chronic inflammatory process that affects the tissues that surround and support the teeth. "For (PI) and Galectin-1, results showed periodontitis and gingivitis groups to have significantly higher values than the healthy group (p < 0.001)." (PMID 38743248, 2024). "The second study uncovers increased levels of soluble urokinase plasminogen activator receptor (suPAR) and galectin-1 in the gingival crevicular fluid of individuals with periodontal disease, especially in chronic periodontitis patients." (PMID 38192959, 2023). "The results showed that concentrations of suPAR and galectin-1 were significantly higher in the GCF of patients with periodontitis and gingivitis compared with periodontally healthy controls." (PMID 34585876, 2021). "Also, Galectin-1 was significantly higher in the periodontitis/gingivitis groups than in the control group." (PMID 38743248, 2024). "Four potential biomarker crosstalk genes were also immune genes, i.e., LGALS1, LSP1, SAMSN1, and WIPF1 between periodontitis and VTE." (PMID 34925639, 2021). "Four biomarker crosstalk genes between periodontitis and VTE were also immune genes, i.e., LGALS1, LSP1, SAMSN1, and WIPF1." (PMID 34925639, 2021). "Galectin-1 and -3 GCF levels were evaluated (before and after non-surgical treatment for periodontitis) using an enzyme linked immune-sorbent assay (ELISA) kit." (PMID 38743248, 2024). "However, in a recent clinical study, Taşdemir et al42 evaluated the levels of suPAR and galectin-1 in the GCF of patients with gingivitis, and periodontitis and compared them with individuals with a healthy periodontal status." (PMID 34585876, 2021). "Therefore, this study will evaluate the impact of non-surgical periodontal treatment on Galectin-1 and -3 GCF levels in patients having periodontitis comparing them with periodontally healthy and gingivitis groups." (PMID 38743248, 2024).
prion disease (5 papers, 2021 to 2023). A transmissible disease that is caused by a protein that is able to induce abnormal folding of normal cellular proteins, leading to characteristic spongiform brain changes, which are associated with neuronal loss without an inflammatory response. "In the study of prion diseases, it was determined that galectin-1 levels in the brain are increased in patients, although the sample size was very small." (PMID 36008956, 2022). "Whereas M1-WT mice showed little change in the expression of APO-E, serpinA3N, clusterin α-chain, and galectin-1 at 16 and 18 w.p.i., M1-PD mice showed a significant increase in all four of these prion disease biomarkers in the hippocampus and/or cortex." (PMID 34893539, 2021). "In addition, molecular markers of neuroinflammation and particularly indicators of astrocyte and microglia activation [such as vimentin, galectin-1, and glial fibrillary acidic protein (GFAP)] were up-regulated in murine prion disease." (PMID 36378750, 2022). "In prion diseases, S-nitrosylated galectin-1 is increased in scrapie-infected rodents and human prion diseases, where neuroprotection of galectin-1 does not appear to function efficiently." (PMID 34720894, 2021). "Galectin-1, especially the S-nitrosylated form of galectin-1, is upregulated in the brains of scrapie-infected rodents and human prion diseases, where astrocytes and neurons, but not microglia, are immunoreactive for galectin-1." (PMID 34720894, 2021). "Galectin-1 and 3 play important roles in the pathogenesis of neuroinflammatory and neurodegenerative disorders such as multiple sclerosis (MS), amyotrophic lateral sclerosis (ALS), Alzheimer's disease (AD), Parkinson's disease, Huntington's disease, and prion disease." (PMID 34720894, 2021).
Stroke (5 papers, 2019 to 2023). Sudden impairment of blood flow to a part of the brain due to occlusion or rupture of an artery to the brain. "After ischemic insult in stroke, galectin-1 treatment sustained neurogenesis in a carbohydrate-dependent manner and this process was inhibited by an anti-galectin-1 blocking antibody." (PMID 36873388, 2023). "The function of galectin-1 was studied in an experimental stroke model and elevated galectin-1 expression was detected in the infarcted and penumbra area." (PMID 36873388, 2023). "In CI model, Galectin-1 regulates neurogenesis in the subventricular zone and promotes functional recovery after stroke." (PMID 35378910, 2022). "Further, Galectin-1 is one of the key regulators of adult neurogenesis through its carbohydrate-binding ability and promotes functional recovery after stroke." (PMID 31156388, 2019). "Furthermore, galectin-1 protected neurons by modulating the expression of the glutamate receptor NMDA, which prevented the neurotoxicity of glutamate during the stroke." (PMID 36873388, 2023).
systemic lupus erythematosus (5 papers, 2019 to 2026). An autoimmune multi-organ disease typically associated with vasculopathy and autoantibody production. "Increased titers of anti-galectin-1 aAbs were reported in autoimmune and infectious neurological disorders and uveitis, Chagas disease and systemic lupus erythematosus (SLE)." (PMID 35008499, 2021).
type 1 diabetes (5 papers, 2022 to 2025). "Given that galectin-1 mediated a glycan-binding dependent suppressive effect on antigen-activated T cells, type 1 diabetes caused by beta-cell-reactive T cells and experimental autoimmune uveitis mediated by Th1 could be alleviated following application of galectin-1." (PMID 37047471, 2023).